MROH1 (maestro heat like repeat family member 1)
Description:
Lysosome fission factor. Recruited to lysosomes by RAB7 (RAB7A or RAB7B) at scission sites and homooligomerizes to mediate the constriction and scission of lysosomal tubules. May sever membranes by inserting amphipathic helices into one bilayer leaflet. Lysosome fission is required to maintain their steady-state number, shape, size, composition and function, and to accomplish regeneration.
Synonyms: HEATR7A; KIAA1833
Tractability: PROTAC: ubiquitination databases record sites on it; its protein half-life has been measured.
Gene: Protein-coding gene on chromosome 8 (144,147,997 to 144,262,470, forward strand). Ensembl gene ENSG00000179832.
Subcellular location: Lysosome membrane
Subcellular location (Human Protein Atlas): Nucleoplasm; Cytosol
Gene Ontology:
Molecular function: membrane destabilizing activity
Biological process: lysosome fission
Cellular component: lysosomal membrane; cytoplasm
Genetic constraint (gnomAD): Loss-of-function variants: 36 observed, 47.41 expected, observed/expected ratio (o/e) 0.76, 90% interval 0.58 to 1. The upper end of that interval is the gene's LOEUF score, 1, which puts it in group 4 of 6, group 1 being the genes least tolerant of losing a copy. Missense variants: 539 observed, 555.91 expected, observed/expected ratio (o/e) 0.97, 90% interval 0.9 to 1.04. Synonymous variants: 268 observed, 245.08 expected, observed/expected ratio (o/e) 1.09, 90% interval 0.99 to 1.21.
Homologues: Orthologues: chimpanzee MROH1 (99% identical), macaque MROH1 (97% identical), pig MROH1 (80% identical), guinea pig MROH1 (80% identical), rat Mroh1 (80% identical), dog MROH1 (80% identical), mouse Mroh1 (79% identical), tropical clawed frog mroh1 (55% identical), zebrafish mroh1 (46% identical). Paralogues in human: MROH2A (27% identical), MROH2B (26% identical), MROH5 (18% identical), MROH7 (16% identical), MROH8 (14% identical), MROH9 (10% identical), MROH6 (10% identical), MRO (4% identical).
Diseases named in the same sentence as MROH1 in open-access papers:
MROH1 is named in the same sentence as 6 diseases in open-access papers, as found by Europe PMC text mining. Sharing a sentence is not in itself a finding about the gene and the disease.
MROH1 shares sentences with these, for which no sentence is quoted: breast carcinoma (1 paper); cancer (1); HIV-1 infection (1); ovarian carcinoma (1); ovarian serous carcinoma (1); tumour (1).